COL2A1 (collagen type II alpha 1 chain)
Diseases named in the same sentence as COL2A1 in open-access papers (continued):
Sharing a sentence is not in itself a finding about the gene and the disease.
skeletal dysplasia (30 papers, 2009 to 2026). Any Mendelian diseases that affects growth and development of the skeleton. "Mutations in the COL2A1 gene have been associated with a spectrum of overlapping skeletal dysplasias, therefore, this participant received a broad diagnosis of a COL2A1 collagen disorder." (PMID 38028619, 2023). "COL2A1-associated skeletal dysplasias are a large group of genetically heterogeneous diseases with an autosomal dominant type of inheritance caused by pathogenic variants in the COL2A1 gene (OMIM:120140)." (PMID 35052477, 2022). "Researchers generated stable transgenic lines expressing the wild-type or mutant version of a gene of interest, such as the ALS-causative G348C mutation in TDP-43 or the C1315Y mutation in COL2A1 associated with lethal fetal skeletal dysplasia." (PMID 35875659, 2022). "COL2A1 pathogenic variants are associated with many skeletal dysplasia, with a series of phenotypes ranging from lethal to relatively mild forms often reported." (PMID 34573377, 2021). "Our case reported a recurrent c.G1636A (p.G546S) mutation of COL2A1 in a Chinese family with skeletal dysplasia." (PMID 28738883, 2017). "Mutations in the type II procollagen gene COL2A1 alone cause at least ten different forms of skeletal dysplasia." (PMID 24086591, 2013). "Embryonic, chondrocyte-specific induction of the mutation using Col2a1-Cre resulted in a skeletal dysplasia affecting the long bones, spine, and craniofacial skeletal elements, consistent with the human skeletal dysplasia phenotypes produced by TRPV4 mutations." (PMID 41574606, 2026). "SEDC is a heterogeneous group of skeletal dysplasias, associated with COL2A1 mutations." (PMID 35692839, 2022). "The significant variability in the clinical manifestations of COL2A1-associated skeletal dysplasias makes it necessary to conduct a clinical and genetic analysis of individual nosological variants, which will contribute to improving our understanding of the pathogenetic mechanisms and prognosis." (PMID 35052477, 2022). "However, we have expanded our understanding of the ratio and occurrence of the COL2A1-associated skeletal dysplasias phenotypes in childhood, including atypical and rare forms, such as dyspondyloenchondromatosis." (PMID 35052477, 2022). "Similarly, mutations in COL2A1 gene result in several rare autosomal dominant clinical entities that share skeletal dysplasia, short stature and sensorial defects." (PMID 29738498, 2018). "Recently, inheritable skeletal dysplasia caused by novel COL2A1 mutations has been linked to an inherited disease of the hip joint that neither involves the entire skeletal system nor is characterized by the presence of concomitant disorders, such as spinal or ocular abnormalities." (PMID 25124518, 2014). "COL2A1-related disorders represent a heterogeneous group of skeletal dysplasias with a wide phenotypic spectrum." (PMID 32071555, 2020). "Tg:Col2a1-Cre;Trip11cko/−;ROSA26mTmG/+ mice display a severe and lethal skeletal dysplasia, the features of which are identical to ACG1A." (PMID 29180569, 2018). "Some of these newly identified genes are well characterized as cartilage-selective and associated with one of a variety of forms of skeletal dysplasia (e.g., TRPV4, COL2A1, COMP, and COL9A3)." (PMID 20046828, 2009). "Analogous patterns are well recognized in other genetic conditions such as COL2A1 (Collagen, Type II, Alpha-1)-related skeletal dysplasias and TBX6 (T-Box Transcription Factor 6)-related segmentation defects, where allelic heterogeneity and modifiers account for wide phenotypic variability." (PMID 41300719, 2025). "Our findings not only demonstrated the efficacy of melatonin in ameliorating abnormal function and cell fate of SLC26A2-deficient chondrocytes in vitro but also underscored its role in partially alleviating the skeletal dysplasia seen in Col2a1-CreERT2; Slc26a2fl/fl mice." (PMID 39759111, 2025).
skeletal dysplasia (continued). "Ex vivo mini-gene analysis shows whether a splice site variant causes a frameshift or exon skipping in the COL2A1 gene, which may be important in determining the phenotype of COL2A1-skeletal dysplasia." (PMID 35052477, 2022). "It is traditionally thought to result from a Collagen Type II Alpha 1 Chain (COL2A1) mutation on chromosome 12q13.1-q13.2; however, recently the Trafficking Protein Particle Complex Subunit 2 (TRAPPC2) gene mutation has also been associated with the skeletal dysplasia." (PMID 35755523, 2022). "Therefore, we propose that the size and position of an in-frame deletion in COL2A1 may be relevant in determining the phenotype of skeletal dysplasia." (PMID 34573377, 2021). "Skeletal dysplasia (SD) is one of the most common inherited neonatal disorders worldwide, where the recurrent pathogenic mutations in the FGFR2, FGFR3, COL1A1, COL1A2 and COL2A1 genes are frequently reported in both non-lethal and lethal SD." (PMID 34789231, 2021).
tumor (29 papers, 2016 to 2025). "Interestingly, the extracellular matrix protein-encoding genes such as FN1, TIMP1, COL3A1, COL4A1, and COL2A1 were discovered in spatial cluster 8, regarded as tumor stroma tissues." (PMID 39257581, 2024). "Interestingly, normalization of upregulated intracellular cholesterol synthesis in Col2a1-CreERT2;Idh1R132Q/R132Q mice by loss of Scap (Col2a1-CreERT2;Idh1R132Q/R132Q;ScapF/F mice), or by treatment with lovastatin, suppresses chondrogenic tumor growth." (PMID 33256181, 2020). "Thus, immune status is important in explaining variation in DFS and OS across multiple cohorts even when patient age, tumor stage, BRCA1/2 somatic mutational status, tumor cytoreduction, and COL2A1 expression is known." (PMID 32156016, 2020). "COL2A1 gene, which encodes the alpha chain of type 2 collagen, has also been observed in DDCS and are likely early events in progression of these tumours." (PMID 37568740, 2023). "On the other hand, collagen molecules were up or downregulated across different tumour subtypes and only COL2A1 was upregulated across all sample groups." (PMID 36220861, 2022). "Immune signatures were also significant (p < 0.05) in the presence of tumor cytoreduction, BRCA1/2 mutation, and COL2A1 expression." (PMID 32156016, 2020). "The dysfunction of COL2A1 may result in abnormalities in matrix deposition and signal transduction pathways, leading to abnormal and uncontrolled divisions and tumour development." (PMID 37568740, 2023). "NROB2 was differentially expressed in TA, which may indicate the expression of NROB2 will inhibit the tumor deterioration, while COL2A1 was differentially expressed in IV, indicating that the expression of this gene may involve some other regulatory mechanisms to inhibit tumor deterioration." (PMID 38459043, 2024). "Moreover, similar to the cartilage matrix, which is rich in type II collagen, the building blocks of the tumor niches may be provided by the availability of type II collagen component, such as COL2A1." (PMID 32962144, 2020). "In stage 7 (sm b stage), PI3K-AKT signaling and EMT signaling (e.g., AKT2/3, COL2A1, etc.)were dominant, of which EMT signaling is involved in tumor-initiation and motility." (PMID 36966136, 2023). "A particularly interesting potential interaction with high relevance for tumor biology includes JAG2 (cancer) with NOTCH3 (mouse stroma), and interactions of integrins (ITGA2, ITGA2B) with ECM proteins (COL2A1, LAMA1)." (PMID 35053442, 2022). "Col1a1, Col1a2, Col2a1, Col3a1, and Col5a2, which were commonly found in normal ECM of mouse, pig, and human breast tissues, were also identified in tumor ECM in addition to Col4a2, Col5a1, Col6a1, Col6a2, Col6a3, and Col7a1." (PMID 36547361, 2022). "Decreased expression of COL2A1 reduces the osteogenic protein, destroys normal ECM structure, promotes the remodeling of the BM microenvironment toward the direction of tumor promotion, and participates in the mutual promotion between TME and AML." (PMID 33898304, 2021). "Additionally, OC’s previously demonstrated ability to stabilize collagen type II alpha 1 chain (COL2A1) expression in OA chondrocytes may hold relevance in CHS, where ECM remodeling and collagen mutations create an immunosuppressive tumor niche enriched in M2 macrophages." (PMID 40564985, 2025). "The fibrillar collagens COL2A1, COL11A1, and COL11A2 show higher expression in the solid tumour region and other fibrillar collagens, COL1A2 and COL3A1, show higher abundance in the brain/tumour interface region." (PMID 38001067, 2023).
tumor (continued). "Notably, among the four genes signature, only the CXCL10 gene was involved in tumor immunity; however, few studies have been conducted in oncology for the other three genes (TRPC7, CUX2, and COL2A1)." (PMID 34276760, 2021). "COL2A1 and FMOD showed very similar expression patterns as ARG2 across sample groups defined by tissue and age status, demonstrating a higher expression level in the young tumor group than in the old tumor group." (PMID 28027300, 2016).
cancer (12 papers, 2016 to 2026). A tumor composed of atypical neoplastic, often pleomorphic cells that invade other tissues. "Considering the emerging roles of COL2A1 in cancer dysregulation, findings of this study support the evaluation of COL2A1 role on FMCs progression, as well as, possible prognostic and therapeutic implications." (PMID 36220861, 2022). "As a result, seven DEGs correlated with more than 10 TR-DDR genes (r>0.3) in at least 10 cancers were regarded as candidate genes, including COL2A1 (the R ranged from 0.39 to 0.60), MAGEA4 (0.24–0.62), FCRL4 (0.33–0.62), ZIC1 (0.24–0.33), LCN15 (0.20–0.41), PRSS3 (0.24–0.35), CSAG1 (0.31–0.38)." (PMID 36081518, 2022). "Fourthly, previous studies revealed that both COL2A1, which encodes a component of type-II collagen and collages, and ZIC1 could suppress cancer metastasis by regulating the signaling pathway of the extracellular collagen-derived antiangiogenic factor and Wnt signaling pathway respectively." (PMID 36081518, 2022). "Top five up-regulated genes in malignant tumours were COL11A1, SFRP2, LCN2, COL2A1 and H19, while top up-regulated genes in benign tumours were MMP3, MMP1, AREG, PTHLH and SFRP2." (PMID 30517191, 2018). "Yet, the downregulation of the type II collagen gene (COL2A1) in PC3SFRP2, which is involved in cancer stemness in various cancer types, and the upregulation of CDH15 (Cadherin 15) in PC3SFRP2, which mediates intracellular adhesion, are promising predictors of the role of SFRP2 in cancer metastasis." (PMID 36552843, 2022).
connective tissue disorder (11 papers, 2013 to 2026). A disease involving the connective tissue. "We compare the phenotypes of our patients with related disorders of connective tissue and discuss possible pathomechanisms and genotype–phenotype correlations for the identified COL2A1 variants." (PMID 35296718, 2022). "These children might be the carrier to the connective tissue disorder due to defective extracellular matrix as seen with COMP, COL2A1, COL9A1, COL9A2, etc. genetic mutation." (PMID 33870477, 2022). "Notably, of the 29 children with nFTS with dysmorphic features resembling connective tissue disorders, 7 had VUSs of genes known to be related to connective tissue (BMP4, MATN3, COL2A1, COL11A1, COL1A1, COL1A2, and COL6A3)." (PMID 40524006, 2025). "High throughput sequencing of 34 genes for hereditary connective tissue disorders did not identify any mutation in FLNB, but did identify a de novo missense mutation in TGFBR2 and a nonsense mutation in COL2A1 that was also present in his unaffected father." (PMID 30170566, 2018). "Other networks significantly enriched also related to a further network in connective tissue disorders that contained genes including collagens COL10A1, COL11A1 and COL2A1 plus a disintegrin and metalloproteinase with thrombospondin motifs-2 (ADAMTS-2) and fibulin-1 (FBLN1)." (PMID 23971731, 2013).
infection (10 papers, 2008 to 2025). The state of being infected such as from the introduction of a foreign agent such as serum, vaccine, antigenic substance or organism. "We found that when SDC4 was overexpressed in normal rat chondrocytes by infection of Lv-Sdc4, the expression of COL2A1 and ACAN were decreased significantly, the expression of MMP3 was increased, both in mRNA and protein levels." (PMID 36414669, 2022). "The expression of Ciart, Per2, Cilp2, Tnmd, Col2a1, and Wif1 at each time point post-infection was significantly different from that observed in uninfected diaphragms (P < 0.0001)." (PMID 33648561, 2021). "Given that chondrocyte dedifferentiation, which is marked by the loss of anabolic factor expression, leads to chondrocyte senescence, we also assessed the mRNA expression levels of the major anabolic factors, Col2a1, Acan, and Sox9, and found that they were decreased by Ad‐Zmiz1 infection." (PMID 40040621, 2025). "Ectopic expression of miR-146a via infection of primary mouse articular chondrocytes with Lenti-mimic 146a reduced the protein levels of type II collagen (Col2a1) and sex determining region Y (SRY)-box 9 (Sox9) in the absence or presence of pro-inflammatory factors." (PMID 28383548, 2017). "In contrast to Sox9 and Col2a1, siCdc5l mildly increased the Wee1 pre-mRNA splicing efficiency, and this enhancement was cancelled by AAV-CDC5L infection in ATDC5 chondrocytes." (PMID 34298017, 2021). "In contrast, infection with the GDF5L373R virus resulted a reduction of inhibitor of differentiation 1 (ID1), which negatively regulates the expression of COL2A1 and SOX9." (PMID 29371961, 2017).
genetic disorder (5 papers, 2008 to 2025). "The immobilization-only genes included collagen genes Col2a1, Col10a1, and Col11a1, all previously associated with human genetic disorders with altered joint mobility." (PMID 26006773, 2015). "Mutations on human genes encoding AAT 19, collagen α−1(II) chain (COL2A1) 20, Niemann-Pick type C1 (NPC1) 21, and dysferlin (DYSF) 22, 23 can cause their misfolding in the ER, leading to degradation by ERQC and various genetic diseases." (PMID 40678220, 2025).
autosomal dominant disease (2 papers, 2021). Autosomal dominant form of disease. "COL11A1‐related autosomal dominant disease was most common in our series, followed by COL2A1‐related autosomal dominant disease." (PMID 33951325, 2021). "COL11A1‐related rather than COL2A1‐related autosomal dominant disease may be more common when undiagnosed children are identified based on ocular examination." (PMID 33951325, 2021). "COL11A1‐related rather than COL2A1‐related autosomal dominant disease may be more common when undiagnosed children are identified based on ocular exam." (PMID 33951325, 2021).
bone cysts (2 papers, 2014 to 2023). "During cartilage morphogenesis, differentiating chondrocytes secrete extensive ECM defined early in resting and proliferating chondrocytes by the expression of col2a1 and defects in the composition or integrity of the ECM cause well-known skeletal diseases/dysplasias." (PMID 37039156, 2023).
COL2A1 also shares sentences with these, for which no sentence is quoted: osteogenesis imperfecta (8 papers); spondyloepimetaphyseal dysplasia (6); Hearing impairment (5); Marfan syndrome (5); vitreoretinal degeneration (5); Czech dysplasia (3); Hip dysplasia (3); spondyloperipheral dysplasia (3); arachnodactyly (2); avascular necrosis (2); campomelic dysplasia (2); cataract (2); CHARGE syndrome (2); craniosynostosis (2); gastric cancer (2); lumbar disc herniation (2); lung carcinoma (2); Onset (2); otospondylomegaepiphyseal dysplasia (2); sensorineural hearing loss (2); spondyloarthritis (2); Stroke (2); type 2 Stickler syndrome (2); Ullrich congenital muscular dystrophy (2); Wagner disease (2); age-related macular degeneration (1); albinism (1); amblyopia (1); anaemia (1); aneurysm-osteoarthritis syndrome (1).
A further 113 diseases each share a sentence with COL2A1 in 1 paper.